CD24 (CD24 molecule)
Diseases named in the same sentence as CD24 in open-access papers (continued):
Sharing a sentence is not in itself a finding about the gene and the disease.
breast cancer (continued). "Flow cytometry was used to assess the expression of putative breast cancer stem cell markers of CD44/CD24 in MDA‐MB‐231 cells and displaying a proportion of 93.77% ± 4.04% of the CD44+/CD24− subpopulation." (PMID 34320274, 2021). "(G) Kaplan–Meier analysis of the DFS of luminal breast cancer patients with standard endocrine therapy after they were stratified into ≥19.5% CD44-/CD24- cells (n = 24) vs. <19.5% CD44-/CD24- cells (n = 23)." (PMID 34318746, 2021). "(C) Metastasis rates in patients with different molecular subtypes of breast cancer after they were stratified into high (≥19.5%) or low frequency of CD44-/CD24- cells." (PMID 34318746, 2021). "HIF-2α expression has been associated with stemness, self-renewal properties, and survival genes in human breast cancer stem cells (CD24−/CD44+) exposed to hypoxia." (PMID 34205080, 2021). "In the case of breast cancer stem cells (BCSCs), Al-Hajj and colleagues prospectively isolated a tumorigenic population of cells from primary human breast cancer using FACs based on the ESA+/CD44+/CD24−/low/lineage− phenotype." (PMID 33572626, 2021). "Peripheral and cytoplasmic, but not nucleoplasmic, localization was observed among MCF-7, MDA-MB-231, and Hs578T breast cancer cell lines, however, the cells with peripheral localization of CD24 were highly differentiated." (PMID 34360932, 2021). "OSM exposure increased CD44 and Snail expression and repressed CD24, Claudin-1 and E-cadherin in breast cancer cells, while promoting migration and 3D tumour sphere formation." (PMID 34361105, 2021). "(B, C) Flow cytometry analysis of the spontaneous conversion of primary human or xenograft breast cancer CD44-/CD24- cells into CD44+/CD24- CSCs in vitro." (PMID 34318746, 2021). "We found that absence of glycosylation at N52 results in loss of peripheral CD24 in MDA-MB-231 and Hs578T breast cancer cells, as well as in HEK293T cells, reminiscent of what we observe for endogenous CD24 in these cells." (PMID 34360932, 2021). "Within breast cancer, the acquisition of tumor stem cell-like features, the formation of tumor spheres and the appearance of a breast cancer stem cell-specific phenotype (CD44+/CD24-) were all promoted by the occurrence of EMT." (PMID 34150623, 2021). "In a miR-200c/141 cluster deletion mouse model of breast cancer, they found that the knockout of miR-200c/141 resulted in an increase in the CD24+/CD29+ and a decrease in the ALDH+ CSC marker, suggesting that these miRNAs regulate breast CSCs." (PMID 33916548, 2021). "Radiation-induced EMT and stemness phenotype were identified using breast cancer stem cells (CSCs) marker (CD24−/low/CD44+) and mammosphere formation assay." (PMID 34217266, 2021). "Increased fraction of CD44+, CD24- CSC and Mucin-1 expression was also reported in breast cancer MCF-7 cells when exposed to tumor associated macrophages." (PMID 33889547, 2021). "Similar results were also demonstrated in BT-474 luminal B breast cancer cells from sphere-formation assay and flow cytometry analysis of CD24−/CD44+ expression." (PMID 33986289, 2021). "(A) A diagram Illustrated the experimental protocol for testing the spontaneous conversion of primary human breast cancer CD44-/CD24- cells into CD44+/CD24- CSCs in vitro." (PMID 34318746, 2021). "(A) Postoperative metastasis rate in the test group of patients with different molecular subtypes of breast cancer after they were stratified by 19.5% of CD44-/CD24- cells." (PMID 34318746, 2021). "Studies have identified CD44+CD24− in breast cancer; CD44+CD24+EpCAM+ in pancreatic or ovarian cancer; and a high expression of neuron stem markers, such as CD133, CD44, and Nestin, and transcript factors, such as SOX2 and OCT4, in GBM." (PMID 34069945, 2021). "Specifically, OAcGD2 was found to be expressed predominantly on CSCs-enriched population (ALDH+ or CD44+CD24− cells) harvested from PDXs of different molecular subtypes of breast cancer." (PMID 35046949, 2021).
breast cancer (continued). "Considering histological types, medullary and metaplastic breast cancers exhibited remarkably increased frequency of BCSCs with CD24- CD44+ and ALDH+." (PMID 34801088, 2021). "Particularly, the higher frequency of CD44-/CD24- cancer cells was a better predictor of delayed breast cancer metastasis (up to 12 years after initial breast cancer diagnosis)." (PMID 34318746, 2021). "Breast cancer MCF-7 cell-line-derived mammospheres were shown to be enriched in cells with a CD44+/CD24– surface profile, consistent with breast cancer stem cells (BCSC)." (PMID 33919234, 2021). "Breast cancer-expressed CD24 was identified as a ligand for the adhesion receptor P-selectin on platelets and endothelial cells, through which it helps in the extravasation of tumor cells in circulation." (PMID 34360932, 2021). "Sorcin silencing in the breast cancer cells decreases the pool of CD44+/CD24– and ALDH1 high CSCs in vitro." (PMID 34869449, 2021). "In breast cancer, expression of Cluster of Differentiation 24 (CD24), a small GPI-anchored glycoprotein at the cell periphery, is associated with metastasis and immune escape, while its absence is associated with tumor-initiating capacity." (PMID 34360932, 2021). "In another study, the frequency of the CD44+/CD24- population—marking breast cancer stem cells (CSCs)—was diminished, and the expression and activation of the pro-inflammatory IL-6/STAT3 pathway reduced after Sdc-1 siRNA knockdown." (PMID 34070901, 2021). "Recently, our group has found that the expression level of USP37 is exceptionally upregulated in CD44+/CD24- phenotype breast cancer stem cells, and can regulate the stemness of breast cancer cell through its interaction with GLI-19." (PMID 33390801, 2021). "Our findings are in agreement with previous studies, showing that the presence of HER2-positive CTCs co-expressing a breast cancer stem cell profile (HER2+/CD44+/CD24(low)) and elevated ALDH1 activity is related to aggressiveness and radioresistance." (PMID 33799422, 2021). "By monitoring the CSC marker CD24 during doxorubicin treatment in MDA-MB-231 breast cancer cells, we have shown the uniform conversion of CD24− population into CD24+ cells, which we have identified as drug-resistant cells." (PMID 34426608, 2021). "TWIST1 directly represses CD24 expression through the E-box element to increase the CD44+/CD24−/low cancer stem–like cell population in breast cancer cells." (PMID 34809669, 2021). "A high expression of the cell surface marker and HA receptor CD44 combined with a low expression of CD24 (CD44+/CD24−/low) marks a breast cancer cell population with a CSC phenotype." (PMID 34070901, 2021). "CD24 modified with sialyl Lewisx (sLex) was shown to mediate P-selectin–dependent rolling in breast carcinoma in vitro and in vivo." (PMID 34360932, 2021). "In studies on breast cancer cell lines in vivo, CD24 was found to act as a ligand for P-selectin on the lung vascular endothelium." (PMID 33276802, 2020). "After stratification of these specimens based on LIPH expression, we found that the percentage of CD44+/CD24− CSCs in LIPH + TNBC specimens was significantly higher than the percentage in the corresponding LIPH‐ breast cancer." (PMID 32618099, 2020). "CD29+/CD24+ status was previously reported to mark the tumorigenic subpopulation of cells in murine mammary tumors." (PMID 32766238, 2020). "Human breast cancer stem cells can be recognized by several surface antigen markers, such as CD24-/CD44+." (PMID 33211707, 2020). "CD44 is overexpressed in breast tumor cells, and the ratio of CD44 to CD24 has been used as a marker for stem cells in breast cancer." (PMID 32699630, 2020). "The genetic inhibition of autophagy decreases the proportion of breast cancer cells with the CD44+/CD24–/low CSC-like phenotype, signifying a role of autophagy in maintaining typical CSCs in breast cancer." (PMID 32391363, 2020).
breast cancer (continued). "In studying the relationship between STAT3 and CSCs, Polyak and colleagues found that the IL-6/JAK2/Stat3 pathway is preferentially active in CD44+CD24− stem-enriched breast cancer cells, where it is required for their growth." (PMID 32391382, 2020). "In MCF‐7 breast cancer cells, CD24 inhibition reduces chemosensitivity to 5‐fluorouracil, and ABC transporter expression appears not to contribute to this mechanism." (PMID 32394616, 2020). "Although the effect of andrographolide on the BCSCs is quite remarkable, its CC50 value of 0.32 mM in the CD24-/CD44+ BCSCs is higher than the doses of most marketed drugs against breast cancer that are effective at a lower concentration." (PMID 33211707, 2020). "In CD44+/CD24- cell lines and the primary culture of patient breast cancer cells, elevation in both expression and phosphorylation of ATM were found." (PMID 33680952, 2020). "Many studies have verified the breast cancer stem cell line with the CD44+/CD24-/ALDH+ marker, and recently the high expression of aldehyde dehydrogenase (ALDH+) was associated to therapeutic resistance." (PMID 33680952, 2020). "CD44 and CD24 have been suggested as suitable markers for the identification of breast cancer stem cells, whereby the phenotype of tumorigenic mammary tumor cells was determined as CD44+/CD24−/low." (PMID 32430004, 2020). "Tumor spheres were cultured by the suspension method, and the CD44+CD24-/low subpopulation, which is recognized as a special stem-like phenotype of breast cancer, was significantly increased in spheres, which was consistent with our previous findings." (PMID 33457406, 2020). "Remarkably, CD24 is a direct target of Wnt1 in breast cancer, while CD47 is an indirect target of Wnt signaling mediated by SNAI1 and ZEB1 in breast cancer." (PMID 33234169, 2020). "STAT3 is centrally important for the maintenance of CD44+/CD24- CSCs in breast cancer, suppression of genes involved in cell proliferation correspondingly reduce STAT3 activation." (PMID 32754274, 2020). "Although CD34+CD38-6, 7, CD133+8 and CD44+CD24-9-11 have been widely used as CSCs markers in human acute myeloid leukemia, brain tumor and breast cancer respectively." (PMID 31892981, 2020). "It has been shown in breast cancer that β-catenin can inhibit tumor immune escape by down-regulating the expression of CD24." (PMID 32765491, 2020). "The luminal subtypes, which constitute the majority of breast cancer cases, are predominantly CD44low/CD24–/low/ALDH–/low." (PMID 32423137, 2020). "When the authors silenced STAT3 in breast cancer cells and co-cultured them with fresh blood-derived DCs, they found that the treatment strongly synergized CD24 and HER2 downregulation in the cancerous cells." (PMID 33322132, 2020). "Exosomes isolated from pleural effusions from breast cancer patients have increased levels of the epithelial marker proteins EpCAM and CD24 compared to controls." (PMID 33322643, 2020). "Among the CSC surface markers, CD44 and CD24 phenotype have been widely employed in breast cancer research." (PMID 32545405, 2020). "The secretion of IL-6 is an important factor for CSC conservation as well as maintenance, and promotes the CD44+/CD24 low phenotype in breast cancer." (PMID 32391363, 2020). "Previous studies have confirmed that miRNAs play an important role in gene regulation in CD44+CD24−/low breast cancer stem cells (BCSCs)." (PMID 33008330, 2020). "For instance, CD24 is a biomarker expressed in breast cancer solid tumor and in hematological malignancies." (PMID 36133621, 2019). "The expression two antigens CD44 and CD24 has recently been used to explain the CSC population in breast cancer and ovarian cancer." (PMID 30818864, 2019). "To evaluate the effect of Gomisin M2 on BCSCs, we first analyzed the activity of Gomisin M2 against the breast cancer stem cells (with the CD44+/CD24- biomarkers) in MDA-MB-231 and HCC1806 cells." (PMID 31612865, 2019).
breast cancer (continued). "CD44 and CD24 are considered putative stem cell markers and expression profiling of selected breast cancer cell lines in this study correlates well with previously performed studies on the same cell lines." (PMID 31430931, 2019). "In certain breast cancers, the cell adhesion protein CD24+ plays a role in the development of distant metastases and is suppressed by metformin in vitro." (PMID 31345259, 2019). "This is in agreement with previous findings showing that the mesenchymal-like breast cancer stem cells are characterized as CD24−/CD44+, while the epithelial-like breast cancer stem cells express high levels of aldehyde dehydrogenase (ALDH)." (PMID 31261917, 2019). "Transition was also reflected by CD44 and CD24 gradual changes (stemness markers often used in breast cancer EMT studies), patterning four readily observed gating populations." (PMID 31811131, 2019). "CDK2 inhibitor can selectively target CD44+CD24- subpopulation and restores chemo-sensitivity in breast cancer." (PMID 31120927, 2019). "Subsequently, populations of CD24+CD29+ cells and CD24+CD49f+ cells were isolated from BRCA1-mutated mammary tumors and displayed self-renewal and tumor-initiating capacity in vivo." (PMID 31619007, 2019). "In this study, we enriched breast cancer stem cells with CD44+/CD24- from MDA-MB-231 and HCC1806 cells through magnetic-activated cell sorting and cultured these in serum-free medium." (PMID 31612865, 2019). "Breast cancer TICs with the canonical CD44+/CD24-/EpCAM+ signature showed massive upregulation of FA biosynthesis enzymes FASN, ACLY, ACC1 and the master regulator SREBP1." (PMID 31661927, 2019). "Similar to GREM1, CD24 correlated with reduced RFS in all breast cancer cases when highly expressed." (PMID 31694641, 2019). "Consistently, the gene expression profile of CD44+CD24−/low breast cancer cells more closely resembles that of CD44+CD24−/low cells from normal breast tissue." (PMID 30959764, 2019). "In breast cancer, CD24−/CD44+ mesenchymal CSCs are typically located toward the invasive edge of the tumor by the tumor-stroma interface, while ALDH1+ CSCs are found in the more interior region." (PMID 31121840, 2019). "Human breast cancer cells express both CD24 and CD44, but MDA-MB-231 cancer cells expressed a high level of CD44 and a very low level of CD24." (PMID 31658701, 2019). "Even breast cancer (BC) Exo have been studied as potential disease biomarkers since high levels of exosomal CD24 were shown in serum from patients." (PMID 31281356, 2019). "In breast cancer, the expression of CD44 and CD24 has been linked to the identification of cancer stem cells, therapeutic responses, and the invasive behavior of tumor cells." (PMID 31357721, 2019). "Recent studies showed that CD44+CD24- cell population (breast cancer stem cell subpopulation) in MCF-7 cells were resistant to tamoxifen treatment, however, tamoxifen resistant cells harbored higher number of CD44+CD24- cell population than MCF-7 cells." (PMID 31120927, 2019). "Circulating tumor cell (CTC) analysis in our PDX model revealed a significant increase in human circulating cells (HLA1+) enriched for breast cancer stem cell marker (CD44+CD24−)." (PMID 31118047, 2019). "The percentage of CD44+CD24− cells is higher in basal-type compared with luminal-type breast cancer; therefore, attempts to target CSCs have mainly focused on the basal subtype." (PMID 31137841, 2019). "Next, we investigated the expression status of the Notch-1, β-catenin, STAT3, CD44, and CD24 markers in doxorubicin resistantMCF7 breast cancer cells (MCF7_DoxR) compared to MCF7 parental cells (MCF7_DoxS)." (PMID 31357721, 2019). "In summary, a gain in NRF1 expression and/or treatment with E2 led to reprogramming of normal breast epithelial cells to acquire the breast cancer stem cell signature CD24−/CD44+." (PMID 30486409, 2018).
breast cancer (continued). "DNA biosensors based on gold-nanoparticles-modified graphene oxide were constructed to detect two biomarkers, human epidermal growth factor receptor-2 (HER2) and the cell surface protein CD24, of breast cancer." (PMID 29597315, 2018). "The CD24+/CD44+ subpopulation upon carcinogenic E2 treatment produced as many as seven different downstream breast cancer progenitor cell subpopulations." (PMID 30486409, 2018). "Our results indicated that the expression of CD24 was a significant poor prognostic factor in ER-positive early breast cancer treated with adjuvant tamoxifen." (PMID 29416796, 2018). "Recently, Li and colleagues reported that tumorigenic breast cancer cells expressing CD44+/CD24-/low have primary resistance to conventional chemotherapy and accordingly their proportion increases after chemotherapy." (PMID 29416796, 2018). "To validate the expression levels of the USP37 gene in breast cancer stem cells, we isolated CD24−/CD44+ cell populations from MCF-7 cell lines by magnetic activated cell sorting (MACS)." (PMID 30482232, 2018). "The current study aimed to investigate the association between tamoxifen resistance and breast cancer stem cells and clinical implications of CD44/CD24 and ALDH1, potential markers for breast cancer stem cell." (PMID 29416796, 2018). "Stable NRF1 overexpressing MCF10A cells, after treatment with a carcinogenic regimen of E2, were grown as mammospheres in B27 medium then flow cell sorted for the breast cancer stem cell signature CD24−/CD44+." (PMID 30486409, 2018). "Many of the genes regulated have previously been shown to correlate with aggressiveness of breast cancer such as CD24, SOX2, Slug, Twist1, CD-133, N-Cadherin, E-Cadherin, FOXC2, ABCG2, c-Myc, IL8, IL6, and IKKβ (activating NF-κB signaling)." (PMID 29552303, 2018). "CD24 is also an important diagnostic and prognosticmarker of cancer given its expression in many tumor types.In some types of cancer, such as breast cancer, CSCs havedecreased CD24 expression." (PMID 29845783, 2018). "CD44+/CD24- or aldehyde dehydrogenase 1 (ALDH1) has been suggested as a potential marker for breast cancer stem cells." (PMID 29416796, 2018). "The immunoexpression of CSCs markers–CD24, and EpCAM were significantly decreased in rat mammary cancer cells after oregano treatment." (PMID 30092754, 2018). "In breast cancer lung metastasis, neutrophils secrete leukotrienes that promote metastasis by expanding the CD24+CD90+ bCSC population in the MMTV-PyMT spontaneous mouse model." (PMID 29734696, 2018). "Nonetheless, a number of studies have shown that CD44 expression is preferentially associated with the undifferentiated or progenitor-like phenotype whereas CD24 is expressed in more differentiated breast cancer cells with a luminal phenotype." (PMID 29510720, 2018). "In this study, we showed that CD44+/CD24–/low BCSCs enriched from HER2-negative breast cancer cells displayed a radioresistant phenotype with HER2 and EGFR overexpression." (PMID 29464036, 2018). "CD24 has been studied in many cancer types including breast cancer, suggesting a poor prognostic role." (PMID 29416796, 2018). "At first glance, our data seems to be in contrast with current assertions that the CD44+/CD24-/low subpopulation with tumor-initiating properties is positively correlated with distant metastasis in breast cancer." (PMID 29416796, 2018). "We recently demonstrated that SIRT7 deficiency activates TGF-β signaling, enhances EMT and promotes lung metastasis, and induces mesenchymal-like CSCs marked with CD44+CD24- in breast cancers, providing a proof of concept of aging-promoted CSC induction." (PMID 30038266, 2018). "The results of our proposed method indicate that let-7a, miR-223, miR-98a, and miR-34a downregulate CD24 expression in cases of breast cancer." (PMID 30013305, 2018).